ATXN1 (ataxin 1)
Description:
Chromatin-binding factor that repress Notch signaling in the absence of Notch intracellular domain by acting as a CBF1 corepressor. Binds to the HEY promoter and might assist, along with NCOR2, RBPJ-mediated repression. Binds RNA in vitro. May be involved in RNA metabolism. In concert with CIC and ATXN1L, involved in brain development (By similarity).
Synonyms: ATX1; SCA1; D6S504E
Tractability: Small molecule: it has a high-quality binding pocket. PROTAC: UniProt records ubiquitination sites on it.
Gene: Protein-coding gene on chromosome 6 (16,299,112 to 16,761,491, reverse strand). Ensembl gene ENSG00000124788.
Subcellular location: Cytoplasm; Nucleus
Subcellular location (Human Protein Atlas): Nucleoplasm; Cytosol; Nucleoli
Gene Ontology:
Molecular function: identical protein binding; poly(G) binding; poly(U) RNA binding; protein binding; chromatin binding; RNA binding; POZ domain binding
Biological process: negative regulation of DNA-templated transcription; nuclear export; brain development; learning; memory; negative regulation of transcription by RNA polymerase II; RNA processing; social behavior; regulation of DNA-templated transcription
Cellular component: cytoplasm; cytosol; nuclear inclusion body; nuclear matrix; nucleolus; nucleoplasm; nucleus; protein-containing complex
Genetic constraint (gnomAD): Loss-of-function variants: 8 observed, 54.76 expected, observed/expected ratio (o/e) 0.15, 90% interval 0.085 to 0.26. The upper end of that interval is the gene's LOEUF score, 0.26, which puts it in group 1 of 6, group 1 being the genes least tolerant of losing a copy. Missense variants: 987 observed, 1,109.7 expected, observed/expected ratio (o/e) 0.89, 90% interval 0.84 to 0.94. Synonymous variants: 514 observed, 494.36 expected, observed/expected ratio (o/e) 1.04, 90% interval 0.97 to 1.12.
Homologues: Orthologues: chimpanzee ATXN1 (99% identical), macaque ATXN1 (97% identical), rabbit ATXN1 (88% identical), dog ATXN1 (88% identical), guinea pig ATXN1 (88% identical), mouse Atxn1 (87% identical), pig ATXN1 (87% identical), rat Atxn1 (86% identical), tropical clawed frog atxn1 (68% identical), zebrafish atxn1a (46% identical), zebrafish atxn1b (36% identical), Caenorhabditis elegans K04F10.1 (11% identical), and 1 more. Paralogues in human: ATXN1L (25% identical).
Diseases named in the same sentence as ATXN1 in open-access papers:
ATXN1 is named in the same sentence as 122 diseases in open-access papers, as found by Europe PMC text mining. Sharing a sentence is not in itself a finding about the gene and the disease. The quoted sentences say what the papers report.
spinocerebellar ataxia type 1 (140 papers, 2009 to 2026). Spinocerebellar ataxia type 1 (SCA1) is a subtype of type I autosomal dominant cerebellar ataxia (ADCA type I) characterized by dysarthria, writing difficulties, limb ataxia, and commonly nystagmus and saccadic abnormalities. "Expansion of the CAG repeats above 44 in the ATXN1 gene causes spinocerebellar ataxia type 1 (SCA1), while more than 35 CAG repeats in the ATXN2 gene is the cause of spinocerebellar ataxia type 2 (SCA2)." (PMID 41149812, 2025). "Spinocerebellar ataxia type 1 (SCA1) is caused by expansion of glutamine(Q) encoding CAG repeats in ATXN1 that results in a toxic gain of ATXN1 function." (PMID 40321775, 2025). "Spinocerebellar ataxia type 1 (SCA1) is a neurodegenerative disease caused by a mutation in the Atxn1 gene and characterized by progressive ataxia, spasticity, ophthalmoplegia, and bulbar symptoms." (PMID 40429839, 2025). "To validate the potency of our algorithm, we predicted PTM-related protein interactions (PTM-PPIs) of ataxin-1, a protein implicated in Spinocerebellar ataxia type 1 (SCA1)." (PMID 40029919, 2025). "Spinocerebellar ataxias are a group of progressive, debilitating, and inherited neurodegenerative diseases caused by unstable expansions of CAG repeats, and spinocerebellar ataxia 1 (SCA1) is affected by instability in the Atxn1 gene." (PMID 40965523, 2025). "The presence of more than 44 CAG repeats in the ATXN1 gene were identified as causative behind spinocerebellar ataxia 1 (SCA1) in 1993." (PMID 38254109, 2024). "We started by classifying the spike train parameters in a mouse model of ataxia caused by a poly-glutamate expansion in the Atxn1 gene, Atxn1154Q/+ mice, that causes spinocerebellar ataxia type 1 (SCA1)." (PMID 39072369, 2024). "Spinocerebellar ataxia type 1 (SCA1) is caused by polyglutamine expansion in the Ataxin 1 (ATXN1) gene." (PMID 39180052, 2024). "Spinocerebellar ataxia type 1 (SCA1) is an autosomal dominant neurodegenerative disease caused by a trinucleotide (CAG) repeat expansion in the ATXN1 gene." (PMID 38125008, 2023). "Spinocerebellar ataxia type 1 (SCA1) is a dominantly inherited neurodegenerative disorder caused by the expansion of CAG repeats in the ATAXIN-1 (ATXN1) gene that is characterized by early and severe pathology in the cerebellum." (PMID 37108212, 2023). "USP7 also interacts with ATXN1, which is associated with spinocerebellar ataxia type 1 (SCA1), an autosomal dominant neurodegenerative disorder characterized by several neurological defects and symptoms." (PMID 35159365, 2022). "Spinocerebellar ataxia type 1 (SCA1) is a fatal neurodegenerative disease caused by the aberrant amplification of CAG repeats in the Ataxin1 (ATXN1) gene." (PMID 35743271, 2022). "Spinocerebellar ataxia type-1 (SCA1) is a dominantly inherited neurodegenerative disorder caused by the abnormal expansion of CAG repeats in the Ataxin-1 (ATXN1) gene." (PMID 36457352, 2022). "Spinocerebellar ataxia type 1 (SCA1) is a progressive neurodegenerative disease caused by a CAG repeat expansion in the gene Ataxin1 (ATXN1)." (PMID 36291186, 2022). "Mutations in the ataxin-1 gene have been associated with the development of spinocerebellar ataxia type 1 (SCA type 1)." (PMID 34428113, 2021). "Toxic gain-of-function mutations in ATXN1 cause the neurodegenerative disorder spinocerebellar ataxia type 1 (SCA1)." (PMID 33478569, 2021). "In mammals, CIC interacts with ataxin-1 (ATXN1), of which the polyglutamine (polyQ)-expanded form causes spinocerebellar ataxia type-1 (SCA1), a neurodegenerative disease." (PMID 32238859, 2020). "ATXN1 is associated with spinocerebellar ataxia 1 and spinocerebellar degeneration by affecting AKT signaling and checkpoint regulation." (PMID 33374967, 2020). "Spinocerebellar ataxia type 1 (SCA1) is an autosomal dominant neurodegenerative disorder caused by the expansion of CAG repeats in ATXN1 gene resulting in an expansion of polyglutamine repeats in the ATXN1 protein." (PMID 31508229, 2019).
spinocerebellar ataxia type 1 (continued). "The abnormal expansion of a CAG-repeat encoding a poly-glutamine (polyQ) tract in ATXN1 gene causes the disease spinocerebellar ataxia type 1 (SCA1)." (PMID 31508229, 2019). "Spinocerebellar ataxia type 1 (SCA1) is a fatal neurodegenerative disease caused by an abnormal expansion of CAG repeats in the Ataxin-1 (ATXN1) gene and characterized by motor deficits and cerebellar neurodegeneration." (PMID 30718999, 2018). "The ATXN1 gene is a causative factor for spinocerebellar ataxia-1 and has been suggested to participate in the highly conserved Notch signalling pathway with regulatory importance for embryonic development." (PMID 29758065, 2018). "For instance, the individual association of DUSP2, DUSP 4, DUSP 6, DUSP 8, DUSP 11, DUSP 13, DUSP 24 has been reported with ataxin-1, which is the causative protein of spinocerebellar ataxia type 1." (PMID 28902166, 2017). "The mutant form of the protein ataxin-1 (ATXN1) causes the neurodegenerative disease spinocerebellar ataxia type-1." (PMID 28212558, 2017). "Polyglutamine (polyQ) expansion in the protein Ataxin-1 (ATXN1) causes spinocerebellar ataxia type 1 (SCA1), a fatal dominantly inherited neurodegenerative disease characterized by motor deficits, cerebellar neurodegeneration, and gliosis." (PMID 28545543, 2017). "Ataxin-1 (ATXN1) is a coregulator protein within which expansion of the polyglutamine tract causes spinocerebellar ataxia type 1, an autosomal dominant neurodegenerative disorder." (PMID 29212253, 2017). "Spinocerebellar ataxia type 1 (SCA1) is caused by a CAG repeat expansion in the Ataxin1 (ATXN1) gene and is one of the most intensely studied dominant ataxias." (PMID 26439486, 2016). "Spinocerebellar ataxia type 1 (SCA1) is an inherited neurodegenerative disease caused by abnormal expansion of trinucleotide CAG repeats in the coding sequence of a causative ATXN1 gene." (PMID 27802273, 2016). "A causative role for HDAC4 has been also described in SCA-1 (Spinocerebellar Ataxia Type 1) as a modulator of Ataxin-1." (PMID 25759639, 2015). "Mutations in the Ataxin-1 encoding gene (ATXN1) cause spinocerebellar ataxia type 1, a neurodegenerative disease." (PMID 26138482, 2015). "Ataxin-1 is the protein responsible for the genetically-inherited neurodegenerative disease spinocerebellar ataxia type-1 linked to the expansion of a polyglutamine tract within the protein sequence." (PMID 23853075, 2014). "Spinocerebellar ataxia 1 (SCA1) is caused by glutamine repeat expansion in the ataxin 1 (ATXN1) gene." (PMID 24865773, 2014). "Huntingtin exon 1 (Htt) and full-length Ataxin-1 (ATXN1) are causative genes of Huntington's disease (HD) and spinocerebellar ataxia type 1 (SCA1), respectively." (PMID 25551764, 2014). "Spinocerebellar ataxia type-1 (SCA1) is an inherited neurological disease caused by expansion of an unstable CAG repeat in the ataxin-1 (ATXN1) gene, which leads to progressive degeneration of Purkinje cells in the cerebellar cortex." (PMID 24252411, 2013). "Spinocerebellar ataxia type 1 (SCA1) is a lethal neurodegenerative disorder caused by expansion of a polyglutamine (poly-Q) tract in ataxin-1." (PMID 24364034, 2013). "ATXN1 (ataxin-1), is well known for causing the dominantly inherited spinocerebellar ataxia type 1 (SCA1; OMIM 164400), mainly due to a gain of function mechanism upon expansion of a (CAG)n repeat." (PMID 23294540, 2013). "Ataxin-1 is the protein responsible for the hereditary spinocerebellar ataxia type 1, a disease linked to protein aggregation and transcriptional dysregulation." (PMID 24155902, 2013). "Spinocerebellar ataxia type 1 (SCA1) is an autosomal dominant neurodegenerative disease that is caused by the expansion of a translated CAG repeat in ATAXIN1 (ATXN1)." (PMID 23936457, 2013). "Ataxin-1 (ATXN1), is a causative gene for spinocerebellar ataxia type 1 (SCA1), with mutation of expanded CAG trinucleotide repeats encoding a polyglutamine tract (polyQ) in the gene." (PMID 23285140, 2012).
spinocerebellar ataxia type 1 (continued). "Here, we focused on the reported interaction between FOX-2 and ataxin-1, the disease-causing protein in spinocerebellar ataxia type 1." (PMID 22666429, 2012). "ATXN1 is an RNA-binding protein present in neuron nuclei; the expansion of its polyglutamine domain causes spinocerebellar ataxia type 1 (SCA1)." (PMID 20700456, 2010). "Spinocerebellar ataxia type 1 (SCA1) is a dominantly inherited neurodegenerative disease caused by expansion of a CAG repeat that encodes a polyglutamine tract in ATAXIN1 (ATXN1)." (PMID 20628574, 2010). "Expansion of the polyglutamine coding CAG repeat in ATXN1 causes spinocerebellar ataxia type 1." (PMID 40624398, 2025). "Similarly, PQBP1 was found to bind to mutated ataxin-1, known to be in association with spinocerebellar ataxia type 1 (SCA1)." (PMID 39205314, 2024). "Ataxin 1 (ATXN1), the protein that causes spinocerebellar ataxia type 1, has an ataxin-1 and HMG-box protein 1 (AXH) sequence, which was initially discovered in the high-mobility group transcription activator HMG1, gave the first evidence tying ATXN1 to transcription." (PMID 36672670, 2023). "Moreover, we detected downgulation of Atxn1 regulon, in which mutations cause spinocerebellar ataxia type 1, an inherited neurodegenerative disease characterized by a progressive loss of Purkinje neurons in the cerebellum." (PMID 37542675, 2023). "Here, we show substantial correlation between brain region-specific levels of expansion of the XDP CCCTCT repeat and the HTT CAG repeat, as previously observed in a similar comparison between expansion of the HTT CAG repeat and of the ATXN1 CAG repeat underlying spinocerebellar ataxia type 1 (SCA1)." (PMID 35395816, 2022). "To learn whether the relation between polyQ expansion and increased S-nitrosylation is specific to Htt, we conducted similar studies of Ataxin-1, which causes spinocerebellar ataxia type 1 (SCA1) when its N-terminal polyQ tract is expanded." (PMID 27658206, 2016). "Mutant ataxin-1 (Atxn1), which causes spinocerebellar ataxia type 1 (SCA1), binds to and impairs the function of high-mobility group box 1 (HMGB1), a crucial nuclear protein that regulates DNA architectural changes essential for DNA damage repair and transcription." (PMID 25510912, 2015). "This “loss-of-function” mechanism was undeniably proven in the case of spinocerebellar ataxia type 1, caused by expansion of a glutamine-encoding repeat in ataxin 1, in which the amount of nuclear deposits of mutant ataxin-1 was shown to inversely correlate with the severity of the disease." (PMID 25437612, 2014). "In addition, miR-19, miR-101 and miR-130 regulate Ataxin 1 (ATXN1) that causes spinocerebellar ataxia 1 (SCA1), when presenting a CAG expansion." (PMID 24348326, 2013). "Spinocerebellar ataxia type 1 (SCA1) is a rare autosomal dominant inherited neurodegenerative disease caused by the expansion of glutamine (Q)-encoding CAG repeats in the gene ATAXIN1 (ATXN1)." (PMID 40141263, 2025). "Spinocerebellar ataxia type 1 (SCA1) is an autosomal dominant neurodegenerative dis-ease caused by the expansion of cytosine–adenine–guanine (CAG) repeats in the ataxin-1 (ATXN1) gene, leading to toxic gain-of-function of the ataxin-1 (ATXN1) protein." (PMID 41463080, 2025). "Ataxin-1 (ATXN1) is a protein in which expansion of its polyglutamine tract causes the neurodegenerative disorder spinocerebellar ataxia type 1 (SCA1) via a gain-of-function." (PMID 40321775, 2025). "Spinocerebellar ataxia type 1 (SCA1) is a fatal neurodegenerative disease caused by an expanded polyglutamine tract in the widely expressed ataxin-1 (ATXN1) protein." (PMID 38512434, 2024). "For instance, miR-130, in combination with other miRNAs, jointly regulates ATXN1, which causes spinocerebellar ataxia type 1 (SCA1)." (PMID 37434949, 2023). "Ataxin-1 (ATXN1), the gene mutated in spinocerebellar ataxia type 1 (SCA1), is another significant candidate genetic variant interacting with birth by CS for anxiety." (PMID 37029353, 2023).
spinocerebellar ataxia type 1 (continued). "Spinocerebellar ataxia type 1 (SCA1) is a paradigmatic neurodegenerative disease in that it is caused by a mutation in a broadly expressed protein, ATXN1; however, only select populations of cells degenerate." (PMID 36577402, 2023). "In spinocerebellar ataxia type 1 (SCA1), phosphorylation of ataxin-1, the causative protein for SCA1, plays a critical role in ataxin-1 aggregation." (PMID 35523582, 2022). "Spinocerebellar ataxia type 1 (SCA1) is a neurodegenerative disease caused by a polyglutamine expansion in the ataxin-1 protein." (PMID 35906672, 2022). "Spinocerebellar ataxia type 1 (SCA1) is an autosomal dominant neurodegenerative disease caused by a polyglutamine expansion in ataxin-1." (PMID 35906672, 2022). "Spinocerebellar ataxia type 1 (SCA1) is a dominantly inherited neurodegenerative disease caused by the expansion of CAG repeats encoding the polyglutamine (polyQ) tract in Ataxin-1 (ATXN1)." (PMID 33554954, 2021). "Purkinje cells are the key neurons in spinocerebellar ataxia type 1 because an expansion of the trinucleotide CAG repeat in the ATXN1 gene leads to nuclear inclusions of the altered mutated protein in these neurons involved in the pathogenesis of SCA1." (PMID 34768779, 2021). "Spinocerebellar ataxia type 1 (SCA1) is a fatal neurodegenerative disease caused by abnormal expansion of glutamine-encoding CAG repeats in the Ataxin-1 (ATXN1) gene." (PMID 33436887, 2021). "Spinocerebellar ataxia type 1 (SCA1) is a polyglutamine disorder caused by CAG repeat expansion within the Ataxin-1 (ATXN1) gene." (PMID 32964235, 2020). "One of these, spinocerebellar ataxia type 1 (SCA1), is caused by a polyQ expansion in the human Ataxin-1 (ATXN1) protein." (PMID 31655597, 2019). "Spinocerebellar ataxia type 1 (SCA1) is an autosomal dominant neurodegenerative disorder caused by an expansion of a polyglutamine tract within the ATXN1 gene." (PMID 30108484, 2018). "Spinocerebellar ataxia type 1 (SCA1) is an autosomal dominant neurodegenerative disease caused by the abnormal expansion of CAG repeats in the coding region of Ataxin1 (ATXN1) gene." (PMID 29975753, 2018). "A pathological poly-glutamine expansion in ATXN-1, causally related to spinocerebellar ataxia type 1 (SCA1), e.g., was found to induce binding of the protein to RBM17 rather than CiC, thereby promoting disease." (PMID 27200083, 2016). "The neurodegenerative disease spinocerebellar ataxia type 1 (SCA1) is caused by aggregation and misfolding of the ataxin-1 protein." (PMID 24711972, 2014). "Ataxin-1 is the protein associated with the human neurodegenerative spinocerebellar ataxia type 1 or SCA1." (PMID 23853075, 2014). "Spinocerebellar ataxia type 1 (SCA1) is a neurodegenerative disorder caused by the expansion of CAG repeats in the ataxin 1 (ATXN1) gene." (PMID 23094141, 2012). "Another important genetic target is the CIC-ATXN1 transcriptional repressor complex, whose gain-of-function occurs via expansion of the ATXN1 polyglutamine stretch, leading to neurodegeneration in spinocerebellar ataxia type 1." (PMID 40416001, 2025). "Spinocerebellar ataxia type 1 (SCA1) is an autosomal dominant inherited neurodegenerative disease caused by the abnormal expansion of glutamine (Q)-encoding CAG repeats in the coding region of the Ataxin-1 (ATXN1) gene." (PMID 40141263, 2025). "Spinocerebellar ataxia type 1 (SCA1) is a rare neurodegenerative disorder, primarily a result of an extended CAG repeat sequence in exon 8 of the ATXN1 gene, which encodes the ataxin-1 protein." (PMID 40544994, 2025). "Crespo-Barreto J., Fryer J.D., Shaw C.A., Orr H.T., Zoghbi H.Y. Partialloss of ataxin-1 function contributes to transcriptional dysregulationin spinocerebellar ataxia type 1 pathogenesis." (PMID 40995446, 2025).